INS (insulin)
Diseases named in the same sentence as INS in open-access papers (continued):
Sharing a sentence is not in itself a finding about the gene and the disease.
Insulin resistance (continued). "Also, hypothyroid subjects usually present with insulin resistance, a condition that might provoke a reduction in glucose intake from neurons and glia, especially in the hippocampus, where there is a high expression of insulin-dependent GLUT4 transporter." (PMID 29743975, 2018). "Although insulin resistance of peripheral tissue was major investigative target of early research into T2DM, researchers subsequently found that defective secretion of insulin is required for normal glucose tolerance to progress toward hyperglycemia." (PMID 29875737, 2018). "In a fasting state, GK exhibited higher levels of plasma glucose and insulin, and reduced released of GLP-1 (0 min), suggesting insulin resistance." (PMID 29325553, 2018). "The reason for the elevated insulin level with moderately increased glucose levels is not known, but could be linked to an enhanced activity of beta cells associated with a degree of peripheral insulin resistance or to a modification of glucagon secretion." (PMID 29795582, 2018). "Women with PCOS had higher serum insulin levels and HOMA-IR, which reflected higher insulin resistance (p<0.001)." (PMID 30540803, 2018). "Another limitation of our study is a use of indirect method of insulin resistance assessment (HOMA-IR), while the euglycemic hyperinsulinemic clamp technique is considered to be a golden standard for insulin sensitivity evaluation." (PMID 30208901, 2018). "Insulin sensitivity in PCOS women is 35 to 40% lower than that in healthy women with similar BMI, such that most PCOS women display insulin resistance and compensatory hyperinsulinemia, which seem to play an important role in PCOS pathogenesis." (PMID 29971102, 2018). "At age 10–12 y, insulin sensitivity was assessed by the Matsuda Insulin Sensitivity Index (ISI) and the homeostatic model assessment of insulin resistance." (PMID 30383280, 2018). "Insulin resistance is a major determinant of T2DM, which involves some defects of response to pancreatic insulin in muscle and liver cell." (PMID 30060458, 2018). "In the present study, we found that inhibition of ceramide de novo production by myriocin treatment reversed insulin resistance induced by HFD, which was manifested by lower HOMA-IR value and by improvement of glucose and insulin tolerance." (PMID 30545025, 2018). "The molecular mechanism by which insulin resistance is induced is through serine phosphorylation of the insulin receptor substrate 1 (IRS-1), thus impairing insulin action." (PMID 29760586, 2018). "In this model, miR-21a expression correlates directly with homeostatic model assessment-insulin resistance (HOMA-IR, index of insulin resistance) and inversely with insulin sensitivity (HOMA-ISI)." (PMID 30347712, 2018). "The CRLS1 mRNA levels in human scWAT negatively correlated with HOMA2 measures of insulin resistance and positively correlated with HOMA2 measures of insulin sensitivity." (PMID 29861389, 2018). "Because a more pronounced hepatic steatosis, inflammatory responses, and hepatocyte cell damage were observed in insulin+hCG-induced PCOS-like rats, our finding suggest that NAFLD seen in PCOS patients is dependent of hyperandrogenism and insulin resistance." (PMID 29719598, 2018). "TNF-α was believed to induce insulin resistance by inhibiting phosphorylation of IRS-1 and Akt substrate 160 on insulin signaling cascade." (PMID 28716139, 2017). "Though the role of TZDs as an insulin-sensitizing treatment conferring benefit to the cardiovascular system would, in theory, be of advantage in future treatments of cardiovascular events associated with high insulin resistance states, clinical trials have not been able to support it." (PMID 28243251, 2017). "It delays and suppresses the metabolic derangements such as insulin resistance and T2DM because of its remarkable insulin-sensitizing property." (PMID 28662701, 2017).
Insulin resistance (continued). "Insulin sensitivity, expressed as glucose-to-insulin ratio and HOMA index that indicate the insulin resistance ([basal glucose] × [basal insulin]/22.5), results significantly improved after 12 weeks of treatment." (PMID 28348586, 2017). "However, it may now be possible to improve hepatic insulin sensitivity through biochemical modulation of this novel ternary effector complex, which may help to circumvent the impaired hepatic autophagy occurring in insulin resistance." (PMID 28740220, 2017). "Further work is needed to understand the interaction among exercise, carbohydrate restriction, insulin sensitivity, and lipid availability, particularly in individuals with IGT who have adipose insulin resistance." (PMID 29387730, 2017). "Evidence from our, and several other, experimental models of insulin resistance and T2DM has revealed impaired insulin-mediated Akt/eNOS-dependent signaling in the vasculature." (PMID 28814745, 2017). "The characteristic lipid profile of chronic insulin resistance includes elevated free fatty acids (FFA), which inhibit the insulin-related suppression of very low density lipoprotein (VLDL) secretion by the liver." (PMID 29163128, 2017). "Four trials estimated insulin resistance in study participants by calculating HOMA-IR from fasting glucose and insulin values." (PMID 28475161, 2017). "Insulin resistance appears to be a key factor of obesity-driven T2DM, and leads to impairments of the action of insulin in target tissues, such as, fat, liver and skeletal muscle." (PMID 28694473, 2017). "Insulin resistance was assessed using a homeostatic model assessment of insulin resistance (HOMA-IR) and serum fasting insulin." (PMID 28704413, 2017). "In Japanese and Korean, impaired early-phase insulin secretion plays more important role in isolated IGT, whereas insulin resistance is dominant in isolated IFG subjects." (PMID 28199386, 2017). "In our study, ferulic acid modulated the glucose dyshomeostasis induced by HFD by reducing the glucose, insulin levels, and HOMA-IR, which contribute to the prevention of insulin resistance and type 2 diabetes." (PMID 28661434, 2017). "Interestingly, insulin has been observed to induce NPRC expression in human adipocytes, and this finding might link conditions associated with hyperinsulinemia, such as obesity and insulin-resistance." (PMID 28946871, 2017). "Given the central role of insulin resistance in the onset of PCOS, insulin-sensitizing agents, such as metformin and pioglitazone, have been proposed as first line approaches." (PMID 28642705, 2017). "Seven participants were identified as having insulin resistance (HOMA-IR >2.6), and 12 participants were identified as being insulin sensitive (HOMA-IR ≤2.6)." (PMID 32153825, 2017). "The body mass index (BMI), Waist/Hip ratio, homeostasis model assessment insulin resistance (HOMA-IR), fasting blood glucose, triglyceride and low-density lipoproteins, and fasting insulin were significantly higher in the PCOS group (p<.05)." (PMID 28400351, 2017). "Meanwhile, metabolic parameters as body weight increase rate, fasting plasma glucose (FPG), fasting insulin (FINS) levels and insulin resistance index (HOMA-IR) were measured." (PMID 28335761, 2017). "Insulin resistance in the brain typically precedes and contributes to cognitive decline above and beyond other known causes of AD and abnormalities in the activity of two major signaling pathways for insulin and insulin-like growth factor in non-diabetic people with AD has been identified." (PMID 28070499, 2017). "Specifically, HOMA-%β is a surrogate for pancreatic β-cell insulin production, HOMA-IR is a measure for insulin resistance, and HOMA-%S is a measure for insulin sensitivity." (PMID 28253317, 2017).
Insulin resistance (continued). "Our results showed that eight weeks of oral administration of HFD has increased serum FFAs by 29.8% (p < 0.01), and serum insulin level by 68.8% (p < 0.01) and HOMA-IR by 75.7% (p < 0.01), indicating that rats the HFD developed distinct insulin resistance." (PMID 28718838, 2017). "Disturbance of the insulin signalling pathways and an increased expression of the serine-phosphorylated insulin receptor substrate 1 (IRS1-pS616), a marker of the insulin resistance, were detected in the hippocampus of the HFD mice." (PMID 28432486, 2017). "Human CRP plays an active role in inducing hepatic insulin resistance in rats, partially by activating extracellular signal-regulated kinase (ERK), with downstream impairment in the insulin signaling pathway." (PMID 28361994, 2017). "Insulin resistance most likely increases during ACS; however, ΔK was positively correlated with plasma glucose level, which overwhelmed insulin resistance condition." (PMID 28430816, 2017). "Other measures include post-prandial glucose concentrations, reflecting insulin secretory responses and HOMA-IR to measure insulin resistance." (PMID 28400713, 2017). "Also, there is some notion from animal models that intrauterine growth restriction may be related to reduced beta-pancreatic cell mass and hence be predisposing, under diets rich in carbohydrates, to inadequate insulin secretion and the resulting insulin resistance." (PMID 31363354, 2017). "Subsequently, insulin resistance was assessed by homeostasis assessment model of insulin resistance (HOMA-IR), quantitative insulin sensitivity check index (QUICKI) and the insulin/triglyceride-derived McAuley index." (PMID 28576138, 2017). "Insulin resistance, a key characteristic of T2DM, is characterized by impaired insulin-mediated glucose disposal in skeletal muscle, hepatic cells or adipose cells." (PMID 28531120, 2017). "Further, the GDM women had a higher estimated insulin resistance, unfavorable lipid ratios (i.e., higher TG/HDL-C, LDL/HDL-C and apoB/apoA), lower estimated insulin sensitivity and lower estimated β-cell function at the 5-year follow-up visit." (PMID 28068986, 2017). "In accordance with a GSNO-induced hypothalamic insulin resistance, GSNO 50 μM suppressed insulin-induced decrease in food intake and body weight in rats." (PMID 28835706, 2017). "Accordingly, the insulin resistance index (HOMA-IR) was found to be almost two-fold lower in AAV-ΔFosB group than control, indicating higher insulin sensitivity." (PMID 28121620, 2017). "Glucose and insulin levels were significantly higher in the HFD group, which is indicative of insulin resistance and consistent with the development of type 2 diabetes." (PMID 29118818, 2017). "To understand the molecular mechanisms contributing to insulin resistance, we further observed the effects of EPF supplementation on these key factors of insulin signaling in liver tissue." (PMID 28867797, 2017). "In addition, bacteria belonging to the genera Collinsella have been reported to be positively correlated with insulin and that it was enriched in T2D patients; therefore, enrichment of Collinsella here might imply the possibility of insulin resistance in obese children." (PMID 29214176, 2017). "Taken together, these results demonstrate that NLRP3 impaired the normal insulin signaling pathway and led to insulin resistance; IL-1β, a downstream molecular of NLRP3, also played a key role in regulating insulin sensitivity." (PMID 29096724, 2017). "In the present study, we found that blood glucose, insulin levels and HOMA-IR increased significantly (p ≤ 0.05) in the HFD group compared to the control group, revealing insulin resistance in the HFD group." (PMID 28867797, 2017). "HFD for 20 weeks significantly increased fast plasma levels of glucose, insulin, cholesterol, NFFA and HOMA-IR, the rats on HFD diet developed central obesity with insulin resistance." (PMID 29236702, 2017).
Insulin resistance (continued). "If these results are robust, then we would expect these and related anti-glycosylation agents to be effective for decreasing insulin resistance by decreasing glycation of IR, IGFR, INS, IGF, and related proteins." (PMID 29207492, 2017). "This pattern was similar to the changing patterns of insulin, C-peptide, and HOMA-IR, which suggests that RY has a more durable influence on ghrelin secretion and improvement of insulin resistance than BI." (PMID 29216250, 2017). "It has been reported that HFD induces obesity and insulin resistance, whereas low doses of intraperitoneal STZ induce mild impairment of insulin secretion, which is similar to the feature in the late stage of T2DM." (PMID 29036927, 2017). "The diabetic patients manifest insulin resistance when the expression and activity of SIRT1 were inhibited in hepatocyte, showing that SIRT1 contributes to hepatic insulin sensitivity." (PMID 27659520, 2017). "Definitely, pleiotropic action on insulin targeting organ is involved in the protective role of HGF on HFD-induced obesity and insulin resistance." (PMID 28273932, 2017). "Insulin resistance (HOMA-IR) and insulin sensitivity (QUICKI) were inversely related with DNA methylation." (PMID 28542303, 2017). "We previously showed that peripheral insulin resistance in high-fat-fed Stk25 transgenic mice compared to wild-type controls is accompanied by hyperinsulinaemia, suggesting that pancreatic β-cells could potentially increase insulin production in response to increased insulin demands." (PMID 28442507, 2017). "Since C1-Ten is upregulated under insulin-resistant and diabetic conditions (i.e., dexamethasone and rodent diabetic models), a chemical inhibitor for C1-Ten PTPase activity might provide a potential therapeutic approach against insulin resistance and type 2 diabetes." (PMID 29259227, 2017). "Ghrelin infusion induced peripheral insulin resistance, as assessed by the GIR, independently of acipimox (P = 0.02), whereas acipimox improved peripheral insulin sensitivity independently of ghrelin (P = 0.005)." (PMID 28198428, 2017). "Nevertheless, it appears that the hepatic insulin resistance revealed by IRHOMA as well as the rise of plasma glucose and insulin in the early phase of OGTT is relatively less in RES compared with SIE." (PMID 28349072, 2017). "Since insulin resistance plays a vital role in the pathophysiology of T2DM, insulin sensitizer agents occupy the first place in the T2DM pharmacopeia, and new agents with this potential effect have been extensively investigated." (PMID 28708105, 2017). "The results showed that IGR subjects with Phlegm-damp, Damp-heat or Qi-deficiency constitution all showed significantly higher serum levels of fasting plasma insulin (FPI), an indicator of insulin resistance." (PMID 28893239, 2017). "BMP4, which is closely related to BMP2 was recently found to be upregulated in the serum of two diabetic mouse models and was proposed to contribute to insulin resistance by inhibiting IRS-1 activation and insulin signaling." (PMID 29222456, 2017). "One primary feature during insulin resistance state is that, it is characterized by inhibition of PI3K-dependent signalling pathway while other insulin-signalling pathways combining the Ras/MAPK-dependent pathways remains active." (PMID 28529547, 2017). "Expression of TNF-alpha, which induces insulin resistance, is reduced by PPAR gamma ligands, suggesting that the insulin-sensitizing effect of TZDs is related to its anti-inflammatory properties." (PMID 28298922, 2017). "Insulin resistance is closely related to chronic kidney disease (CKD), and the insulin level can disturb ketogenic activities." (PMID 28814987, 2017). "Serum insulin concentrations and β-cell functions (HOMA-β) were significantly lower (p < 0.05) while serum fructosamine concentrations and peripheral insulin resistance (HOMA-IR) were significantly higher in the DBC group compared to the NC group." (PMID 27937039, 2017).
Insulin resistance (continued). "With regard to the effect of islets Miro1 on insulin resistance, We observed fasting blood glucose (FBG), fasting serum insulin (FINS) levels and homeostasis model assessment of the insulin resistance index (HOMA-IR)." (PMID 29207597, 2017). "Homeostasis model assessment of β-cells function (HOMA-β), insulin sensitivity (HOMA-IS) and insulin resistance (HOMA-IR) were also calculated in all participants." (PMID 28732499, 2017). "After oral administration of MBBP, however, insulin levels significantly declined; the 20% MBBP treatment had the best effect on the improving insulin resistance." (PMID 28970780, 2017). "Homeostasis model assessment of insulin resistance (HOMA-IR) was calculated from glucose and insulin concentrations; HOMA-IR = fasting glucose level (mg/dl) × fasting insulin level (ng/ml)/405." (PMID 29115981, 2017). "Thirdly, HBK001 can attenuate hyperglycemia and improve insulin resistance via increasing endogenous GLP-1 levels and directly stimulating insulin secretion, all of which cannot be achieved by linagliptin treatment." (PMID 28659588, 2017). "High AGE-containing diets induce insulin resistance; on the other side, AGE restriction in food ameliorates insulin signaling, and increases sirtuin-1 expression and AGER-1 that mitigate deleterious gene expression elicited by the AGE/RAGE axis." (PMID 29018354, 2017). "Fasting insulin, fasting glucose to fasting insulin ratio (FGIR), oral glucose tolerance test (OGTT), quantitative insulin sensitivity check index (QUICKI), HOMA IR and HOMA B were used to assess the insulin resistance in this study sample." (PMID 28754153, 2017). "In addition, the brain insulin resistance and the attenuated insulin signaling pathway (p-IRS/ p-AKT/p-GSK-3β) were accompanied by an augmentation in GSK-3β level, which in turn may contribute in the extensive alterations of Tau phosphorylation along with changes in PP2A level." (PMID 28505155, 2017). "Insulin metabolism as well as insulin-altering therapies in Alzheimer’s disease are modulated by APOE status, while irisin reduces diet-induced obesity and insulin resistance in vivo." (PMID 29143599, 2017). "Both olanzapine and clozapine produced significant dose and time dependent effects on fasting plasma glucose and insulin concentrations, HOMA-IR values, insulin resistance and glucose intolerance." (PMID 29209160, 2017). "Mice on a ND were more insulin sensitive than mice fed a HFD, indicating the development of obesity-related insulin resistance." (PMID 29116160, 2017). "CXCL5 by blocking insulin signaling pathway through activating the pathway of Jak2/STAT5/SOCS2, plays an important role in the development of insulin resistance." (PMID 29387827, 2017). "After 10 weeks of HFD feeding, with and without MnP treatment, Intraperitoneal glucose tolerance test (IPGTT) and Insulin tolerance test (ITT) were performed, in order to assess glucose intolerance and insulin resistance." (PMID 29104232, 2017). "In support, HSP72 expression was reduced in muscle under obese and insulin resistant status, and muscle-specific HSP72 overexpression protects against obesity-induced insulin resistance and glucose intolerance." (PMID 29285313, 2017). "Fasting serum level of 25(OH) D, glucose, insulin, calcium, malondialdehyde (MDA), protein carbonyl (PC), also homeostasis model assessment for insulin resistance (HOMA-IR) and fasting glucose to insulin ratio (FGIR) were measured." (PMID 29202122, 2017). "Homeostatic model assessment value for insulin resistance (HOMA-IR) was calculated from the basal levels, indicating an improved insulin sensitivity in both SCFA and in tendency also in the dietary fibre groups." (PMID 28733671, 2017). "Our results implicate FMO5 as a regulator of body weight and of glucose disposal and insulin sensitivity and, thus, identify FMO5 as a potential novel therapeutic target for obesity and insulin resistance." (PMID 28646079, 2017).